SPAG5 (sperm associated antigen 5)
Diseases named in the same sentence as SPAG5 in open-access papers (continued):
Sharing a sentence is not in itself a finding about the gene and the disease.
triple-negative breast carcinoma (8 papers, 2019 to 2024). An invasive breast carcinoma which is negative for expression of estrogen receptor (ER), progesterone receptor (PR), and human epidermal growth factor receptor 2 (HER2). "Likewise, depletion of SPAG5 in the SUM-159PT triple-negative breast cancer cell line markedly reduced cell cycle-associated proteins, such as cyclin A, cyclin B, and the cellular proliferation marker Ki-67, as well as counteracts mitotic spindle formation." (PMID 33230261, 2021). "Further empirical studies have revealed that MYCBP interacts with SPAG5 enhancing c-MYC transcriptional activity in triple-negative breast cancer." (PMID 34277412, 2021). "Second, we depleted (using siRNAs) the expression of three main effectors of the pathway, YAP, TAZ, and TEAD, in MCF-10A cells stably overexpressing SPAG5, and in three different triple-negative breast cancer cell lines, MDA-MB-231, MDA-MB-468, and SUM-159PT." (PMID 33230261, 2021). "However, the contribution of SPAG5 to anthracycline- and taxane-based chemotherapy in triple-negative breast cancer (TNBC) remains controversial." (PMID 38610947, 2024). "Sperm-associated antigen 5 (SPAG5), primarily described as a component of the mitotic spindle required for entry into anaphase, acts as a driver oncogene in various cancer types, including triple-negative breast cancer." (PMID 33230261, 2021). "SPAG5 interacts with MYCBP to elevate the transcriptional activity of c-MYC, thereby accelerating DNA repair and tumor growth of triple-negative breast cancer." (PMID 38807081, 2024). "For example, SPAG5 was significantly overexpressed in triple-negative breast cancer (TNBC) tissues, and overexpression of SPAG5 promoted tumor growth in vitro and in vivo." (PMID 35138218, 2022). "Knocking down SPAG5 increased the S-phase cell population and decreased the expression of c-MYC target genes, including the DNA repair proteins RAD51 and BRCA1/2 in triple-negative breast cancer." (PMID 36304306, 2022). "Viability assay further validated the oncogenic potential of SPAG5, which was counteracted either by miR-10b-3p overexpression or by SPAG5 depletion in line with the results from SUM-159PT triple-negative breast cancer cell line." (PMID 33230261, 2021). "However, the role of SPAG5 in triple-negative breast cancer (TNBC) remains controversial, and evidence for SPAG5-mediated chemoresistance in TNBC is lacking." (PMID 38610947, 2024).
gastric cancer (6 papers, 2020 to 2024). A primary or metastatic malignant neoplasm involving the stomach. "Mechanistically, SPAG5 facilitates the progression of gastric cancer cell via intensifying the Wnt/β-catenin/survivin signaling in vitro and in vivo." (PMID 34796102, 2021). "SPAG5 overexpression was an independent predictor of poor prognosis in gastric cancer patients." (PMID 34796102, 2021).
lung adenocarcinoma (6 papers, 2020 to 2023). A carcinoma that arises from the lung and is characterized by the presence of malignant glandular epithelial cells. "SPAG5 is an emerging oncogene that is overexpressed and exerts carcinogenic effects in diverse cancers such as lung adenocarcinoma and liver cancer." (PMID 36118675, 2022). "For example, LINC00857 modulated lung adenocarcinoma progression by targeting miR-1179/SPAG5." (PMID 33661995, 2021). "LINC00857 via targeting the miR-1179/SPAG5 axis could regulate apoptosis in lung adenocarcinoma." (PMID 34367998, 2021). "LncRNA-LINC00857 by targeting miR-1179/SPAG5 axis could regulate glycolysis in lung adenocarcinoma." (PMID 33123468, 2020).
bladder urothelial carcinoma (5 papers, 2019 to 2022). "Recent study stated that sperm‐associated antigen 5 (SPAG5) activated AKT/mTOR signalling in bladder urothelial carcinoma, indicating SPAG5 might regulate autophagy and play a role in podocyte damage." (PMID 31957155, 2020). "For example, SPAG5 promoted cell proliferation and reduced cell apoptosis in bladder urothelial carcinoma via regulating Wnt3/AKT/mTOR pathway." (PMID 35138218, 2022). "SPAG5 promotes proliferation and suppresses apoptosis in bladder urothelial carcinoma at least partially via up-regulating Wnt3 by activating the AKT/mTOR signaling pathway." (PMID 31985007, 2020). "Furthermore, SPAG5 was shown to confer resistance to cisplatin-induced apoptosis in bladder urothelial carcinoma cells." (PMID 36304306, 2022). "In addition, another study in bladder urothelial carcinoma indicated that SPAG5 overexpression conferred resistance to cisplatin." (PMID 30736840, 2019).
glioma (4 papers, 2016 to 2022). A benign or malignant brain and spinal cord tumor that arises from glial cells (astrocytes, oligodendrocytes, ependymal cells). "In this study, we reported that SPAG5 overexpression was associated with the clinical poor prognosis of glioma patients in TCGA database." (PMID 34796102, 2021). "Increased SPAG5 expression is linked to unfavorable prognosis in glioma patients." (PMID 36118675, 2022). "Knockout of SPAG5 restrains proliferation, colony formation, migration, and invasion of glioma cells and stimulates apoptosis." (PMID 36118675, 2022). "In short, we show that increased expression of SPAG5 in glioma was closely correlated with poor prognosis, indicating that SPAG5 serves as a promising prognostic factor in glioma." (PMID 34796102, 2021). "We next analyzed the relationship between the mRNA expression of SPAG5 and clinic characteristics, including age, sex, and grade in 667 glioma patients." (PMID 34796102, 2021). "This suggests that in glioma cells, the SPAG5 gene regulates tumor cell proliferation through the CDH2 signaling pathway." (PMID 34796102, 2021). "Though we described that SPAG5 is related to proliferation, migration, and invasion of glioma cells at the molecular and cellular levels, the exact mechanism is not clear." (PMID 34796102, 2021). "Our results provided the evidence that downregulation of SPAG5 represses glioma cell proliferation and attenuates glioma cell migration and invasion in vitro." (PMID 34796102, 2021). "In the glioma cell lines (U87 and U251) transfected with SPAG5-shRNA, cell apoptosis was significantly enhanced compared with that of the normal control group." (PMID 34796102, 2021). "SPAG5 is a promising prognostic factor and potential therapeutic target for clinical intervention in glioma." (PMID 34796102, 2021). "Glioma patients with low expression of SPAG5 showed a higher overall survival rate than glioma patients with high expression of SPAG5 [log-rank P = 0.03; hazard ratio (HR) = 3.324, CI 2.521–4.328]." (PMID 34796102, 2021). "Analysis of the mRNA expression profiles of SPAG5 in TCGA revealed that the mRNA expression of SPAG5 was higher in glioma tissues (n = 667) than that in normal tissues (n = 10) (P < 0.05)." (PMID 34796102, 2021). "This analysis suggested SPAG5 as a potential candidate for future vaccine development in melanoma, glioma, prostate, bladder, breast, and head and neck cancers." (PMID 27549193, 2016). "The function of SPAG5 in glioma was analyzed using U87 and U251 cells." (PMID 34796102, 2021). "Knocking down SPAG5 could inhibit the proliferation and colony formation and promoted the apoptosis of glioma cells." (PMID 34796102, 2021). "The biological function of SPAG5 in glioma was next studied." (PMID 34796102, 2021). "The relationship between SPAG5 expression level and clinic characteristics in glioma patients." (PMID 34796102, 2021). "Overexpression of CDH2 with SPAG5 depletion could restore the proliferation and inhibit the apoptosis of glioma cells, which also promoted cell migration and invasion." (PMID 34796102, 2021). "Our data suggest that SPAG5 is an oncogene that promotes glioma by downregulating CDH2." (PMID 34796102, 2021). "Our findings imply that SPAG5 plays a role in the development of gliomas." (PMID 34796102, 2021). "Whether SPAG5 has an effect on glioma after overexpression and in vivo experiments are our next step need further investigation to unveil the mechanism." (PMID 34796102, 2021). "Furthermore, the overall survival between glioma patients with low (n = 334) and high (n = 333) expression of SPAG5 was compared, who were grouped according to the median of the expression of SPAG5." (PMID 34796102, 2021). "Notably, SPAG5 depletion by shRNA silencing led to reduced proliferation and viability of the glioma cells." (PMID 34796102, 2021).
glioma (continued). "Our results revealed that SPAG5 knockdown could reduce CDH2 expression, and overexpression of CDH2 could antagonize the effects of SPAG5 knockdown in glioma cells." (PMID 34796102, 2021). "The increased expression of SPAG5 was correlated with poor outcomes in glioma patients." (PMID 34796102, 2021). "In addition, SPAG5-depleted glioma cells displayed increased apoptosis in vitro." (PMID 34796102, 2021). "However, the clinical significance of SPAG5 and its biological role in glioma remain obscure." (PMID 34796102, 2021). "SPAG5 may represent a potential therapeutic target for the clinical intervention of glioma." (PMID 34796102, 2021). "Furthermore, our findings suggested that glioma cells overexpressing SPAG5 were more aggressive." (PMID 34796102, 2021). "Thus, it is deduced that SPAG5 may also take part in the tumorigenesis and progression of glioma." (PMID 34796102, 2021). "Our results demonstrated that deletion of the SPAG5 gene reduced the expression of CDH2 and inhibited the proliferation of glioma cells, whereas restoration of CDH2 restored the proliferation of glioma cells." (PMID 34796102, 2021).
lymph node metastasis (4 papers, 2016 to 2021). "SPAG5 expression is significantly associated with the clinical stage, lymph node metastasis, Gleason score, and BCR." (PMID 33708770, 2021). "High SPAG5 expression was associated with increased lymph node metastasis and high risk of local recurrence." (PMID 30736840, 2019). "High SPAG5 expression was significantly associated with lymph node metastasis, clinical stage, Gleason score, and BCR." (PMID 27037000, 2016). "We identified that SPAG5 expression was gradually increased in PCa progression and its level was significantly associated with lymph node metastasis, clinical stage, Gleason score, and biochemical recurrence." (PMID 27037000, 2016). "Furthermore, we found that high SPAG5 expression was associated with increased lymph node metastasis (p = 0.040) and increased risk of local recurrence (p = 0.009) in TNBC." (PMID 30736840, 2019). "Univariate analysis showed that high SPAG5 expression, pathological grade, lymph node metastasis, distant metastasis, and TNM staging were correlated with DFS and long-term survival of patients with ovarian cancer." (PMID 31985007, 2020).
non-small cell lung carcinoma (4 papers, 2014 to 2024). A group of at least three distinct histological types of lung cancer, including non-small cell squamous cell carcinoma, adenocarcinoma, and large cell carcinoma. "And miR-1179 was also found to suppress cell growth and invasion by targeting SPAG5 in human non-small cell lung cancer." (PMID 32131767, 2020). "Analysis of cancer/testis antigen expression and CD8 T-cell abundance suggests that MAGEA3 is a potential immune target in melanoma, but not in non-small cell lung cancer, and implicates SPAG5 as an alternative cancer vaccine target in multiple cancers." (PMID 27549193, 2016).
osteosarcoma (4 papers, 2021 to 2024). A usually aggressive malignant bone-forming mesenchymal neoplasm, predominantly affecting adolescents and young adults. "SPAG5 silencing inhibited migration, invasion, and epithelial-mesenchymal transition of osteosarcoma cells, which is attributed to regulating the FOXM1/MMP2 axis." (PMID 38807081, 2024). "Moreover, it has been reported that SPAG5 contributes to metastasis of osteosarcoma by activating FOXM1/MMP2 signaling." (PMID 35342412, 2022). "In vitro, SPAG5 silencing inhibits the EMT process of osteosarcoma cells, and SPAG5 may serve as a prognostic indicator and potential therapeutic target for patients with osteosarcoma." (PMID 34796102, 2021).
bladder cancer (3 papers, 2020 to 2022). "In vivo, it targeted the protooncogenic target SPAG5 gene, to effectively inhibit the progression and growth of bladder cancer by reducing SPAG5 levels." (PMID 34162370, 2021). "Next, we performed a preliminary analysis of the downstream signaling pathway by which SPAG5 regulates bladder cancer cell growth and progression." (PMID 34162370, 2021). "In summary, we have developed FeSiNTs nanoparticles for siRNA targeted delivery to treat bladder cancer cells that overexpress SPAG5." (PMID 34162370, 2021). "These nanoparticles can efficiently avoid endosome degradation and deliver the therapeutic siRNA into the cytoplasm rapidly, resulting in significantly inhibited expression of SPAG5 expression and reduced bladder cancer progression and growth." (PMID 34162370, 2021). "Thus, FeSiNTs/siSPAG5-mediated SPAG5 silencing exerted its anti-tumor effect by reducing the migration and invasiveness of bladder cancer cells in vitro." (PMID 34162370, 2021). "Accordingly, our previously data suggested that SPAG5 upregulation could be detected frequently in primary bladder cancer tissues and high SPAG5 expression was identified a novel independent prognostic marker for patient survival." (PMID 34162370, 2021). "Previously, we noted that in bladder cancer, SPAG5 is involved the AKT/mTOR pathway." (PMID 34162370, 2021). "Thus, SPAG5 might regulate bladder cancer proliferation and progression via the downstream PI3K/AKT/mTOR signaling pathway." (PMID 34162370, 2021).
breast tumor (3 papers, 2020 to 2021). "This might be partially due to the aberrant expression of SPAG5 (sperm-associated antigen 5) in breast tumour cells, as we previously reviewed." (PMID 33801148, 2021). "Our results showed that SPAG5 mRNA expression was increased 4.29 times in breast tumors than the NATs." (PMID 32838814, 2020). "We also found that in matched breast tumor and nontumor tissues, lower levels of miR-10b-3p were associated with higher SPAG5 protein expression." (PMID 33230261, 2021).
melanoma (3 papers, 2016 to 2022). A malignant, usually aggressive tumor composed of atypical, neoplastic melanocytes. "The expression of SPAG5 in malignant melanoma (MM) tissues and matched normal tissues was detected using qRT-PCR, immunohistochemistry and Western blotting." (PMID 35138218, 2022). "A study has revealed that downregulation of SPAG5 suppresses the ADAM17/NOTCH1 pathway by lowering the expression of FOXM1 in malignant melanoma (MM), thereby dampening the viability, migration, invasion, and EMT of MM cells." (PMID 36118675, 2022). "In this study, we aimed to reveal the role of SPAG5 in melanoma and clarify whether FOXM1 (forkhead box protein M1) /ADAM17 (A disintegrin and metalloproteinase 17) /NOTCH1 signaling was involved." (PMID 35138218, 2022). "We conjectured that SPAG5 may also modulate FOXM1 expression in melanoma." (PMID 35138218, 2022).
ovarian carcinoma (3 papers, 2020 to 2022). A malignant neoplasm originating from the surface ovarian epithelium. "Although there was only one research paper found focusing on the gene SPAG5, the correlation of this gene with the ovarian cancer had been explored deeply in the paper." (PMID 34143800, 2021). "Although there was only 1 research paper found focusing on the gene SPAG5, the correlation of SPAG5 with the ovarian cancer had been explored deeply in the paper." (PMID 34143800, 2021). "Further studies including studies on larger sample sizes and those examining the biological roles of SPAG5 in ovarian cancer invasion and metastasis are necessary." (PMID 31985007, 2020). "SPAG5 mRNA expression in ovarian cancer tissues was approximately 4.5-fold that in paracancerous tissues." (PMID 31985007, 2020). "The results showed that compared with the endogenous control gene GAPDH, SPAG5 expression levels in ovarian cancer tissues and paracancerous tissues were 5.36 ± 4.25 and 1.20 ± 1.21 (P = 0.002), respectively." (PMID 31985007, 2020). "In summary, the present study is the first full manuscript to report the relationship between SPAG5 expression and clinicopathological features in ovarian cancer, especially its prognosis in details." (PMID 31985007, 2020). "The present study focused on the relationship between SPAG5 expression and the clinicopathological characteristics and prognosis of ovarian cancer." (PMID 31985007, 2020). "qPCR, WB, and IHC analyses were used to study the mRNA and protein expression levels of SPAG5 in ovarian cancer." (PMID 31985007, 2020). "The correlation between SPAG5 expression and the clinicopathological characteristics and prognosis of ovarian cancer patients was investigated." (PMID 31985007, 2020). "In the GSE40595 and GSE14407 datasets, SPAG5 mRNA expression was significantly higher in ovarian cancer tissues than that in normal ovarian tissues (both P < 0.001)." (PMID 31985007, 2020). "qPCR and immunohistochemistry showed that SPAG5 expression in ovarian cancer tissues was significantly higher than that in paracancerous tissues (P = 0.002, P < 0.001)." (PMID 31985007, 2020). "The IHC assay showed that ovarian cancer tissues from 56 of 102 cases exhibited high SPAG5 expression and that paracancerous tissues from 42 cases had high SPAG5 expression; the difference was significant (P < 0.001)." (PMID 31985007, 2020). "SPAG5 protein expression levels in ovarian cancer and paracancerous tissues was detected using WB and IHC." (PMID 31985007, 2020). "The expression of SPAG5 protein in a tissue microarray containing 102 cases of ovarian cancer was detected by immunohistochemistry." (PMID 31985007, 2020). "The expression levels of SPAG5 mRNA were significantly different between wild-types and mutant ovarian cancers (P < 0.001)." (PMID 31985007, 2020). "Consistent with the qPCR results, WB detection showed that SPAG5 expression in ovarian cancer tissues was significantly higher than that in paracancerous tissues." (PMID 31985007, 2020). "Our study also found that SPAG5 is correlated with the clinicopathological features of ovarian cancer, including histological type, lymph node and distant metastasis, TNM staging, and prognosis." (PMID 31985007, 2020). "Our study also lacks the support of a large-scale sample size, and subsequent studies on in vivo and in vitro models to investigate the biological role of SPAG5 in ovarian cancer invasion and metastasis and the regulation of related signaling pathways are underway." (PMID 31985007, 2020). "Whether SPAG5 can be used as a new marker for the diagnosis and prognosis of ovarian cancer was the focus of the present study." (PMID 31985007, 2020). "Subsequently, qPCR test was used to detect SPAG5 mRNA expression in 20 cases of ovarian cancer." (PMID 31985007, 2020). "Therefore, the carcinogenic function of SPAG5 in ovarian cancer has been confirmed." (PMID 31985007, 2020).